IL11 (interleukin 11)
Description:
Cytokine that stimulates the proliferation of hematopoietic stem cells and megakaryocyte progenitor cells and induces megakaryocyte maturation resulting in increased platelet production. Also promotes the proliferation of hepatocytes in response to liver damage. Binding to its receptor formed by IL6ST and IL11RA activates a signaling cascade that promotes cell proliferation. Signaling leads to the activation of intracellular protein kinases and the phosphorylation of STAT3. The interaction with the membrane-bound IL11RA and IL6ST stimulates 'classic signaling', whereas the binding of IL11 and soluble IL11RA to IL6ST stimulates 'trans-signaling'.
Synonyms: IL-11; AGIF
Tractability: Small molecule: a structure with a bound ligand is known. Antibody: UniProt places it where antibodies can reach, with high confidence; its Gene Ontology location is reachable by antibodies, with high confidence; UniProt predicts a signal peptide or a membrane-spanning region.
Gene: Protein-coding gene on chromosome 19 (55,364,382 to 55,370,463, reverse strand). Ensembl gene ENSG00000095752.
Subcellular location: Secreted
Pathways (Reactome):
Immune System: IL-6-type cytokine receptor ligand interactions
Gene Ontology:
Molecular function: cytokine activity; growth factor activity; protein binding; interleukin-11 receptor binding
Biological process: interleukin-11-mediated signaling pathway; negative regulation of endothelial cell apoptotic process; negative regulation of hormone secretion; positive regulation of cell population proliferation; positive regulation of MAPK cascade; positive regulation of peptidyl-serine phosphorylation; positive regulation of peptidyl-tyrosine phosphorylation; positive regulation of transcription by RNA polymerase II; regulation of complement-dependent cytotoxicity; B cell differentiation; fat cell differentiation; megakaryocyte differentiation; negative regulation of cytokine activity; negative regulation of cytokine-mediated signaling pathway
Cellular component: extracellular region; receptor complex; cytoplasm
Genetic constraint (gnomAD): Loss-of-function variants: 16 observed, 12.94 expected, observed/expected ratio (o/e) 1.24, 90% interval 0.83 to 1.8. The synonymous counts are far from expectation, so gnomAD's model fits this gene poorly and the ratio says little. Missense variants: 270 observed, 203.32 expected, observed/expected ratio (o/e) 1.33, 90% interval 1.2 to 1.47. Synonymous variants: 133 observed, 93.16 expected, observed/expected ratio (o/e) 1.43, 90% interval 1.24 to 1.65.
Homologues: Orthologues: chimpanzee IL11 (100% identical), macaque IL11 (94% identical), dog IL11 (93% identical), pig IL11 (93% identical), guinea pig IL11 (90% identical), mouse Il11 (88% identical), rat Il11 (87% identical), tropical clawed frog il11 (33% identical), zebrafish il11a (24% identical), zebrafish il11b (22% identical).
Diseases named in the same sentence as IL11 in open-access papers:
IL11 is named in the same sentence as 326 diseases in open-access papers, as found by Europe PMC text mining. Sharing a sentence is not in itself a finding about the gene and the disease. The quoted sentences say what the papers report.
breast cancer (144 papers, 2007 to 2026). A primary or metastatic malignant neoplasm involving the breast. "In primary breast cancer tumors, IL-11 was found to be expressed in 17% of the primary breast tumors examined, with a significant association between IL-11 expression and low tumor grade (grades 1–2) (p = 0.05)." (PMID 39125732, 2024). "IL-11 activates osteoclastogenesis in breast cancer bone metastasis-associated osteolysis through the JAK1/STAT3/c-Myc pathway." (PMID 37199584, 2023). "Bone matrix-induced TGF-β enhances the expression of IL-11 and other osteoclast differentiation factors in breast cancer cells, thereby further increasing the rate of bone loss." (PMID 37199584, 2023). "Elevated levels of IL-11 (~ 250 μg/l) have been identified in breast cancer patients which is associated with bone metastasis." (PMID 35484352, 2022). "Expression analysis of IL-11 and its receptor in human breast cancers revealed that their high levels are clinically associated with lower survival." (PMID 35163731, 2022). "IL-11 is produced by breast cancer cells and has been implicated in breast cancer-induced osteolysis." (PMID 34201209, 2021). "Through high‐throughput RNA sequencing analysis, we have also found that the cytokine interleukin‐11 (IL11) is the main factor linking BCAHC‐1 cells to breast cancer‐associated fibroblasts (CAFs)." (PMID 34841688, 2021). "Therapeutic options for breast cancer patients at risk of progressing to bone metastasis are necessary, but IL-11-based therapy requires more extensive analyses to confirm and extend its use." (PMID 34201209, 2021). "In contrast, Smad4 mainly contributes to breast cancer bone metastasis formation through transcriptional activation of IL‐11, a gene implicated in bone metastasis." (PMID 33377651, 2020). "IL-11, a member of the IL-6 family, is an osteolytic factor produced by breast cancer cells, and its expression seems to be associated with the development of bone metastases." (PMID 31847214, 2019). "Overall, our results revealed the essential role and the underlying molecular mechanism of IL-11 in breast cancer bone metastasis mediated osteolysis." (PMID 31040267, 2019). "In this study, we present both in vivo and in vitro evidences to clarify the essential roles and the underlying molecular mechanisms of IL-11 in breast cancer bone metastasis mediated osteolysis." (PMID 31040267, 2019). "Elevated levels of IL-11 have been documented in primary human breast cancer as well as in breast cancer cell lines and are associated with poor prognosis in breast cancer patients." (PMID 28856117, 2017). "Interleukin (IL)-11, a cytokine produced by breast cancer, has been implicated in breast cancer-induced osteolysis (bone destruction) but the mechanism(s) of action remain controversial." (PMID 23311882, 2013). "IL11 and IL11Rα transcript levels are linked to breast cancer prognosis - breast tumours with a poor prognostic index show a high level of IL11." (PMID 20553623, 2010). "This led to the hypothesis that IL-11 may be associated with bone metastasis development in human breast cancer." (PMID 34201209, 2021). "Moreover, the expression of IL-1β, IL-6, IL-8 or IL-11 in breast cancer cells has been associated with their metastatic potential and aggressive behavior." (PMID 33809315, 2021). "Moreover, the expression if IL‐11 was also reported to down‐regulate the expression of miR‐30c in primary breast tumours while the reduction of IL‐11 was also associated with the relapse‐free survival in breast cancer patients." (PMID 32860492, 2020). "Our data reveal an miRNA-dependent regulatory axis that links the well-known tumor suppressor miR-124 to IL-11-induced osteolysis, which when disrupted in breast cancer might be associated with bone metastasis development and subsequently a poor prognosis." (PMID 29343249, 2018). "Thus, this study implies that IL-11 may be a promising therapeutic target for breast cancers linked to NRF2." (PMID 40584290, 2025).
breast cancer (continued). "Further research revealed that miR-124, which is significantly downregulated in breast cancer bone metastases, inhibits osteoclastogenesis and suppresses bone metastasis through direct targeting of its downstream gene, IL-11." (PMID 41230330, 2025). "Among them, IL-1β, IL-6, IL-8, IL-11, and IL-17 have been extensively validated as mediators of bidirectional communication between bone cells and breast cancer cells, making them potential therapeutic targets." (PMID 41230330, 2025). "A focal point on interleukin signaling pathways, particularly IL-11, can pave the way for fresh therapeutic pathways to prevent and address breast cancer bone metastasis." (PMID 39125732, 2024). "As an activator of osteoclast differentiation, IL-11 has been an important factor for breast cancer metastasis to the bone." (PMID 38323010, 2024). "IL-6: Supports cancer cell proliferation and survival; also promotes osteoclast differentiation, which leads to bone resorption.IL-8: Enhances the invasiveness and migration of breast cancer cells.IL-11: Contributes to osteoclastogenesis and bone resorption." (PMID 39605887, 2024). "Overexpression of miR-124 inhibits the activity of IL-11 which prevents bone metastasis in breast cancer patients." (PMID 38726321, 2024). "Specifically, Interleukins (ILs) such as IL-6, IL-8, IL-1β, and IL-11 have been identified as important regulators in the onset and advancement of breast cancer spreading to the bones." (PMID 39125732, 2024). "Kitamura and team linked higher IL11 protein levels with Nrf2 expression in human breast cancer and found that Keap1-null MEFs in three-dimensional culture elevate Il11, which crucially impacts tumor engraftment and is reduced by Il11 knockout." (PMID 39286246, 2024). "The current study reveals a novel regulatory mechanism through which piR-2158 involved in the interaction between AP-1 transcriptional complex and the promoter of IL11 in human breast cancer cells." (PMID 37153732, 2023). "MiR-379 and miR-204, both identified in this study as potential oncosuppressors, are key regulators of TGF-β-induced IL-11 production, important in breast cancer bone metastasis." (PMID 37508580, 2023). "Patients with breast cancer-related bone metastasis exhibit increased serum levels and mRNA expression of IL-11, suggesting that IL-11 is involved in bone metastasis via STAT3 phosphorylation." (PMID 37199584, 2023). "In a mice model of cancer-induced bone metastasis, overexpression of IL-11 in breast cancer cell lines increased tumor burden and osteolytic lesions." (PMID 37199584, 2023). "The role of IL-11 expression was first studied in primary breast cancer, which developed metastasis into the bone." (PMID 37240247, 2023). "IL-11 also influences breast cancer (BC)-related bone metastases, and its expression is upregulated through the Smad2/3 and p38 MAPK pathway activation by the TGF-β/TGF-βR axis." (PMID 38352248, 2023). "Activation of STAT3 signaling by IL-11 in breast cancer was recently reported to promote tumor invasion and metastasis." (PMID 37153732, 2023). "IL-11, as a pleiotropic cytokine, plays important roles in a number of cancers including colon and breast cancer." (PMID 37153732, 2023). "IL-11 is essential for promoting osteolysis in breast cancer bone metastasis via RANKL-independent osteoclastogenesis by activating the JAK1/STAT3 signaling pathway." (PMID 37199584, 2023). "MafG accelerates cell proliferation and inhibits cell apoptosis in lung adenocarcinoma, while MafF promotes tumor invasion through heterodimerizing with Bach1 and activating the IL11/STAT3 pathway in breast cancer." (PMID 37491302, 2023). "Studies have shown that TGF-ß increases the secretion of osteoclast-stimulating ILs (IL-11 and IL-8) in breast cancer cells." (PMID 35158995, 2022).
breast cancer (continued). "DGUOK-AS1 regulates the microRNA miR-204-5p, whose principal downstream target is interleukin-11; in this context, the RNA was found to promote IL-11 secretion, breast cancer cell migration, angiogenesis, and macrophage migration." (PMID 35741778, 2022). "Accordingly, serum levels of IL-11, STAT3 and TGF-β were higher in patients with metastases to the bone compared with patients with only primary breast cancer, with the metastatic group showing associated poorer survival outcomes." (PMID 35053592, 2022). "In this review, we examine evidence from pre-clinical studies that correlate enhanced IL-6 and IL-11 mediated gp130/STAT3 signaling to the progression of breast cancer." (PMID 35053592, 2022). "IL-11 plays an essential role in breast cancer bone metastases by inducing osteoclastogenesis via JAK1/STAT3 signaling pathway independent of RANKL." (PMID 35994202, 2022). "Both clinical and preclinical studies have reported that IL-6 and IL-11 released from breast cancer cells contributed to the development of bone metastasis." (PMID 35428832, 2022). "High IL-11 expression has been particularly observed in breast cancer patients with bone metastasis and the detection of IL-11 in primary breast cancer has been proposed as a predictive factor for tumor growth in that secondary site." (PMID 35163731, 2022). "In the context of breast cancer, IL-11 neutralizing antibodies appear to downregulate MMP genes and upregulate EMT signatures in the triple negative MDA-MB-231 cell line." (PMID 35053592, 2022). "The action of osteoclasts on bone remodeling releases TGF-β into the metastatic microenvironment which, in turn, stimulates the production of IL-11 and other osteoclast differentiating factors in breast cancer cells." (PMID 35053592, 2022). "In this review, we summarize the role of the IL-6 cytokine family—specifically IL-6 itself, LIF, OSM, and IL-11—as relevant players during breast cancer progression." (PMID 35163731, 2022). "In recent years, numerous studies have shown that IL-11 has a relevant role in breast cancer bone metastasis development." (PMID 35163731, 2022). "In this context, miR-204, miR-211, and miR-379 have been identified as key regulators of the TGF-ß-induced production of IL-11 in bone metastatic MDA-MB-231 breast cancer cells." (PMID 35158995, 2022). "In particular, LPA induces IL-11 expression in MDA-MB231 breast cancer cells and this process seems to be related to the involvement of the PKCδ signalling pathway." (PMID 34201209, 2021). "In 180 breast cancer patients, IL-11 expression level was shown to be significantly increased in the serum of patients with bone metastases compared to patients without metastases, and this is associated with shorter overall survival." (PMID 34201209, 2021). "Some miRNAs, a class of key posttranscriptional regulators, have been described to inhibit IL-11 signalling in different diseases as well as in breast cancer." (PMID 34201209, 2021). "IL11 was found to be positively associated with immune cell infiltration in HCC, while IL11RA was associated with a better prognosis in breast cancer." (PMID 35145511, 2021). "Pollari and colleagues elucidated the role of miRNAs in the bone metastatic process of breast cancer and specifically analysed the miRNAs that regulate TGFβ-induced IL-11 expression." (PMID 34201209, 2021). "Here, the authors screened several hypoxia inducible genes and identified the oncogenic role of MAFF in breast cancer metastasis and that it activates IL11/STAT3 pathway." (PMID 34262028, 2021). "In vitro experiments reveal that TGFβ-dependent IL-11 induction is critical to provide bone metastases phenotype to breast cancer cells." (PMID 34201209, 2021). "Conversely, Oprelvekin, a recombinant human IL-11, is now routinely used to treat thrombocytopenia in breast cancer patients, which underwent radiation therapy, as an alternative to platelets transfusion." (PMID 34201209, 2021).
breast cancer (continued). "TGF-β and BMP2 signaling plays significant roles throughout breast cancer (BC) development and promote metastasis by triggering bone metastasis genes IL11 and CTGF in vivo." (PMID 34326372, 2021). "Subsequently, there were growing evidences that IL-11 is overexpression in other cancer types, such as gastric cancer, breast cancer, endometrial cancer 18-20, suggesting a critical role of IL-11 in cancer progression." (PMID 34149927, 2021). "Other authors reported that miR-124 inhibits breast cancer bone metastasis through the repression of IL-11." (PMID 34201209, 2021). "The authors propose miR-124 and IL-11 as new therapeutic targets for breast cancer patients at an early stage and prognostic markers in advanced stage patients with bone metastasis." (PMID 34201209, 2021). "Here, we review and discuss the role of the best-validated ILs (IL-1β, IL-6, IL-8 and IL-11) involved in the bone cell—breast cancer cell crosstalk during the early events of breast cancer bone metastasis." (PMID 33809315, 2021). "First, we verified that anti-human IL-11 antibody detected endogenous IL-11, using lysates of the human breast cancer cell line MDA-MB-231 that constitutively produce IL-1137, in the presence of control or human Il11 siRNAs." (PMID 33863879, 2021). "This study demonstrates the oncogenic role of MAFF as an activator of the IL11/STAT3 pathways in breast cancer." (PMID 34262028, 2021). "Breast cancer cell is known to produce numerous osteolytic factors, including parathyroid hormone-related protein (PTHrP), IL-1, IL-6, IL-8, IL-11, VEGF, connective tissue growth factor (CTGF), MMP1, HGF, etc.." (PMID 34201209, 2021). "MiR-30a inversely correlates with interleukin-11 expression in breast cancer, with low interleukin-11 correlating with relapse-free survival." (PMID 34361056, 2021). "In vitro experiments utilizing IL-11-neutralizing antibody were reported in breast cancer cells with promising results." (PMID 34201209, 2021). "Reportedly, miR-124 also inhibits bone metastasis by suppressing interleukin 11 (IL11) expression in breast cancer cells, regulating osteoclastogenesis, and reducing osteolysis." (PMID 34072894, 2021). "These authors identified miR-204, -211, and -379 as the strongest modulators of IL-11 production, these miRNAs directly downregulate a key pathogenetic process in breast cancer metastasis, i.e., the TGFβ-induced expression of IL-11." (PMID 34201209, 2021). "On the other hand, high expression of SMAD4 in the MDA-MB-231 breast cancer cell line has been seen to increase the basal level of IL-11 on stimulation by TGF-β1." (PMID 34297787, 2021). "Recent studies have also shown that microRNA miR-124 reduces the survival of MDA-MB-231 breast cancer cells in the in vivo bone microenvironment and repressed cancer cell-induced osteolytic disease after intratibial injection via downregulation of IL-11." (PMID 33809315, 2021). "miR-206/TWF1/MKL1-SRF/IL-11 signaling pathway played an important role in breast cancer initiation and progression." (PMID 34345203, 2021). "Another prominent IL involved in breast cancer colonization and initiation of osteolytic disease in bone is IL-11." (PMID 33809315, 2021). "In an in vitro experiment, it has been reported that LPA enhances breast cancer cell-mediated osteoclastogenesis by inducing the secretion of osteolytic cytokines, such as IL-8 and IL-11." (PMID 34201209, 2021). "IL-11 released by breast cancer cells is able to stimulate osteoclast differentiation and increases osteoclast progenitor cells." (PMID 34201209, 2021). "Some cytokines (IL-1, IL-6, IL-11) stimulate while others (IL-12, IL-18, IFNs) inhibit breast cancer proliferation and/or invasion." (PMID 32887217, 2020). "TGF-β is an important factor that is released during bone resorption, which stimulates tumor cells to express factors such as CTGF, IL-11, and PTHrP, which are necessary for the metastasis of breast cancer cells to the bone." (PMID 32117996, 2020).